ENSG00000239008
Synonyms: LOC124900504
Gene: Small nucleolar RNA gene on chromosome X (80,857,076 to 80,857,202, reverse strand). Ensembl gene ENSG00000239008.
Gene Ontology:
Biological process: RNA processing
Cellular component: nucleolus
Homologues: Paralogues in human: SNORA78 (83% identical).